CS (citrate synthase)
Description:
Key enzyme of the Krebs tricarboxylic acid cycle which catalyzes the synthesis of citrate from acetyl coenzyme A and oxaloacetate.
Tractability: PROTAC: UniProt records ubiquitination sites on it; ubiquitination databases record sites on it; its protein half-life has been measured.
Target class: Enzyme; Transferase
Gene: Protein-coding gene on chromosome 12 (56,271,699 to 56,300,391, reverse strand). Ensembl gene ENSG00000062485.
Subcellular location: Mitochondrion matrix
Subcellular location (Human Protein Atlas): Mitochondria
Pathways (Reactome):
Metabolism: Citric acid cycle (TCA cycle); Maturation of TCA enzymes and regulation of TCA cycle
Metabolism of proteins: Mitochondrial protein degradation
Protein localization: Mitochondrial protein import
Gene Ontology:
Molecular function: citrate synthase activity; identical protein binding; RNA binding; acyltransferase activity, acyl groups converted into alkyl on transfer
Biological process: carbohydrate metabolic process; tricarboxylic acid cycle; citrate metabolic process
Cellular component: extracellular exosome; mitochondrial matrix; mitochondrion; nucleus
Genetic constraint (gnomAD): Loss-of-function variants: 12 observed, 54.64 expected, observed/expected ratio (o/e) 0.22, 90% interval 0.14 to 0.36. The synonymous counts are far from expectation, so gnomAD's model fits this gene poorly and the ratio says little. Missense variants: 265 observed, 543.32 expected, observed/expected ratio (o/e) 0.49, 90% interval 0.44 to 0.54. Synonymous variants: 146 observed, 205.03 expected, observed/expected ratio (o/e) 0.71, 90% interval 0.62 to 0.82.
Homologues: Orthologues: chimpanzee CS (99% identical), macaque CS (99% identical), dog CS (97% identical), rabbit CS (96% identical), pig CS (96% identical), rat Cs (95% identical), guinea pig CS (95% identical), mouse Cs (94% identical), mouse Csl (90% identical), tropical clawed frog cs (88% identical), zebrafish cs (88% identical), Drosophila melanogaster kdn (70% identical), and 2 more.
Diseases named in the same sentence as CS in open-access papers:
CS is named in the same sentence as 161 diseases in open-access papers, as found by Europe PMC text mining. Sharing a sentence is not in itself a finding about the gene and the disease. The quoted sentences say what the papers report.
Obesity (28 papers, 2013 to 2026). Accumulation of substantial excess body fat. "In liver, there was also a trend for reduced citrate synthase activity due to HFD associated obesity (P = 0.086) but both exercise and NMN led to significant increases relative to the HFD vehicle group (both P < 0.001)." (PMID 27594836, 2016). "This difference in obesity resistance between the strains might also be associated with CS activity since the chromosome substitution strain, which carries chromosome 10 of the A/J strain on B6 strain background, is also obesity resistant." (PMID 30944739, 2019). "Mitochondrial oxygen consumption rates and citrate synthase specific activity are also significantly decreased in WAT of individuals with obesity, and this negatively correlates with BMI and body weight (BW)." (PMID 40522819, 2025). "Obesity group was lower than Con group in the concentrations of placental adenosine triphosphate, citrate synthase, and complex I activity." (PMID 34497775, 2021). "Changes in PGC1α and CS in response to high-fat feeding and obesity have been mixed, with some studies demonstrating an increase and others showing a decrease." (PMID 32545529, 2020). "In general, both CS activity and mitochondrial mass decrease in obesity, and CS activity correlates with mitochondrial mass." (PMID 31965758, 2020). "Gut microbiota appears to play a key role in the development and progression of obesity, together with changes in citrate synthase activity." (PMID 27894254, 2016). "A significant correlation between citrate synthase level and obesity, together with a decreased activity of this enzyme in the mitochondria of human omental adipose tissue, were reported in obese humans." (PMID 27894254, 2016). "Adipose tissue citrate synthase activity decreased in obese rats per g wet weight, but citrate synthase per fat pad increased about 2-fold in obesity due to the increase in fat pad size." (PMID 23527196, 2013). "Moreover, 8 weeks of combined aerobic and strength training increased mitochondrial energy production in scWAT, and elevated citrate synthase activity in women with obesity." (PMID 40522819, 2025). "Based on our results exercise might be acting as a regulator of CS/COX ratio, which might represent an important mechanism regulating adipocyte formation and reducing the risk of obesity." (PMID 34327858, 2021). "Citrate synthase activity per liver increased 65% supporting the idea that the enlarged liver also has more mitochondria, but this change was not proportional to the increase in the liver mass, which was increased 107% in obesity." (PMID 23527196, 2013). "To identify the mechanism by which GTE exerts its anti-obesity effects in zebrafish, we measured 3-HAD and CS activity levels in the liver and skeletal muscle of female adult zebrafish." (PMID 25785691, 2015). "In summary, the results of our study suggest that CS activity is of particular importance for metabolic health but affects neither energy balance nor preponderance to obesity in mice." (PMID 30944739, 2019). "While obesity appears to enhance FA transport and oxidation predominately in SSM by an increase of FAT/CD36, CS, and β-hydroxyacyl-CoA dehydrogenase activities with unaltered CPT1, the absence of obesity and presence of T2DM lead to enhancement of FA oxidation only in IFM by CPT-I." (PMID 28850625, 2017). "Similarly, compared to non-obese individuals, individuals with obesity showed a significant decrease in oxygen consumption and citrate synthase activity in adipocytes and adipose tissue from omental and SAT of obesity." (PMID 37920803, 2023). "Further, although citrate synthase activity was not increased, diet-induced obesity increased expression of the mitochondrial biogenesis marker PGC1-α in both the DHpc and PFC, indicative perhaps of a compensatory response to counteract reduced mitochondrial respiration." (PMID 38163062, 2023).
Obesity (continued). "Increased metabolic demands in cancer could be responsible for obesity-related mitochondrial dysfunction since there were no changes in the protein level of PDH and citrate synthase in the CAAT of obese women with malignant tumors." (PMID 38247846, 2024).
breast carcinoma (16 papers, 2018 to 2024). "ACO2-overexpression causes antiproliferation to breast cancer cells, accompanied by a decreasing lactate level, increasing acetyl-CoA level, activating citrate synthase (CS), rising levels of TCA cycle metabolites for citrate, α-ketoglutarate, fumarate, and inducing mitochondrial superoxide." (PMID 35624775, 2022). "Under hypoxic conditions, breast cancer cells accumulate citrate through upregulation of PFKP and citrate synthase, and cytoplasmic citrate promotes breast cancer cell migration, invasion, and metastasis." (PMID 37444501, 2023). "In hypoxic breast cancer cells, the ubiquitination and degradation of CS are diminished, resulting in elevated CS activity." (PMID 37176148, 2023). "Overexpression of CS has been identified in various cancer phenotypes such as prostate, testicular, gastric, pancreatic and breast cancer." (PMID 32961706, 2020). "Loss of citrate synthase via ubiquitination by UBR5, leads to an accumulation of citrate in the cytosol during hypoxia, which leads to the activation of AKT signaling resulting in increased invasion and metastasis of breast cancer cells." (PMID 32867711, 2020). "Previous findings have reported that CS expression is amenable to interference using shRNA approaches, as seen for CS-mediated regulation of the BRCA1 protein in breast cancer cells." (PMID 33807987, 2021). "Up-regulation of phosphofructokinase (PFKP) and citrate synthase (CS) were found to enhance the activity and expression of MMP2 and MMP9 to promote breast cancer metastasis." (PMID 32839493, 2020). "It is paradoxical that high citrate synthase (CS) K393 and 395succ significantly inhibits the proliferation and migration of colon cancer cells, and the detection of increased SIRT5 expression levels in lung cancer and breast cancer." (PMID 38882606, 2024). "To determine if one specific type of cell surface HSPG (CS-HSPG) could be responsible for the negative action of HS on ATXβ cell binding, we first screened by real-time PCR the expression levels of mRNAs for all 10 CS-HSPG (4 SDC; 6 GPC) in human osteosarcoma, prostate and breast cancer cell lines." (PMID 30237860, 2018).
Insulin resistance (16 papers, 2013 to 2025). Increased resistance towards insulin, that is, diminished effectiveness of insulin in reducing blood glucose levels. "CS is a key mitochondrial enzyme involved in energy-producing metabolic pathways, and decreased CS activity is associated with insulin resistance and impaired lipid metabolism in skeletal muscles." (PMID 36213227, 2022). "It has been hypothesized that an inborn defect in the CS enzyme can limit complete fatty acid oxidation in muscle cells and thus cause insulin resistance in type 2 diabetes." (PMID 30944739, 2019). "Increased mitochondrial enzyme activity (e.g., cytochrome c oxidase, citrate synthase) promotes greater β‐oxidation of fatty acids, reducing the accumulation of toxic by‐products like ceramides and diacylglycerides that promote insulin resistance." (PMID 40654205, 2025). "Alterations in mitochondrial biomarkers, defined as cytochrome c (CC), acylcarnitine (AC), and citrate synthase (CS), have been used as reliable biomarkers of mitochondrial dysfunction, with a direct link to insulin resistance." (PMID 39456699, 2024). "Several studies have reported mitochondrial oxidative dysfunction in subjects with impaired glucose tolerance and insulin resistance, although down-regulation of citrate synthase activity was only detected in in vitro myocyte culture." (PMID 25036091, 2014). "Interestingly, increased plasma lactate levels and decreased citrate synthase activity have been reported in skeletal muscle and adipose tissue in insulin resistance and T2D." (PMID 33198288, 2020). "Citrate synthase is not only used by researchers as a biomarker of mitochondrial function but there are even studies suggesting that hereditary citrate synthase dysfunction in skeletal muscle may be responsible for the pathogenesis of insulin resistance and diabetes." (PMID 35328751, 2022). "Insulin resistance reduced mitochondrial function, peroxisome proliferator-activated receptor gamma coactivator 1-alpha mRNA, and citrate synthase expression mRNA, but not protein expression." (PMID 39057712, 2024). "Despite higher expression levels of muscle PGC1α and CS, high-fat diet-induced insulin resistance can still occur, as it is independent of changes in skeletal muscle mitochondrial (fat) oxidative capacity or muscle mitochondria function." (PMID 32545529, 2020). "In the iPS cells, differences in citrate synthase activity resolved after addition of exogenous oxaloacetate, indicating that substrate availability might be limiting for TCA cycle metabolism in insulin resistance." (PMID 26948272, 2016). "In the iPSCs, differences in citrate synthase activity are reversed after exogenous oxaloacetate administration, indicating that availability of substrate might be limiting for tricarboxylic acid (TCA) cycle metabolism in insulin resistance." (PMID 33198288, 2020). "Another facet of BCAA-induced insulin resistance is related to increased BCAA catabolism in the muscle, which leads to incomplete fatty acid oxidation, gives rise to SCAC that allosterically inhibit citrate synthase, results in mitochondrial stress and impairs insulin action." (PMID 27241713, 2016).
diabetes (14 papers, 2007 to 2026). "The data of respiratory chain complexes I and II, ATP generation rates, and citrate synthase activity measurement were analyzed for a possible association with age, gender, obesity, or diabetes." (PMID 24555156, 2013). "For diabetes, citrate synthase (CS) and malate dehydrogenase 1 (MDH1) impaired glucose oxidation via the TCA cycle, while hexose-6-phosphate dehydrogenase (H6PD) disrupted gluconeogenesis." (PMID 41531306, 2026). "Red vastus lateralis muscle citrate synthase activity exhibited a main effect of diabetes (F = 14.59, p < 0.05) and training (F = 4.532, p < 0.05)." (PMID 38435452, 2024). "In the case of diabetes, an increase in citrate synthase protein levels in mitochondria was observed (+29.2%; P = 0.023), while the citrate synthase activity remained unaffected (−5.4%; P = 0.247)." (PMID 24555156, 2013). "This decrease in ceramide levels may alleviate ER stress, upregulate citrate synthase (CS) expression, downregulate pyruvate carboxylase (PC)expression, and further inhibit gluconeogenesis, ultimately preventing the onset of diabetes." (PMID 39726876, 2024). "Citrate synthase (CS) is a mitochondrial enzyme whose inefficiency may be partly responsible for the pathogenesis of diabetes." (PMID 36213227, 2022). "The measurements of citrate synthase activities did not reveal any associations with age (P = 0.862), gender (P = 0.145), or diabetes (P = 0.247)." (PMID 24555156, 2013). "In combination with the sensitivity of both the diabetes-induced changes in RCR and citrate synthase to desipramine reported here, we strongly argue that ASM plays a key role in RPE cell mitochondrial dysfunction." (PMID 32481596, 2020). "In diabetes, including GDM, the increase in citrate synthase activity in the myometrium, coexisting with the lower protein content in the myometrium, may reduce or suspend uterine contractions during labor." (PMID 33142800, 2020).
malaria (14 papers, 2007 to 2025). Malaria is a serious and sometimes fatal disease caused by a parasite that commonly infects a certain type of mosquito which feeds on humans. "Three selected heterogeneous studies conducted during the 1980s evidenced an association between anti-CS antibodies and age and therefore seem to reflect the cumulative exposure to malaria-infected mosquitoes." (PMID 28270152, 2017). "A strong association between anti-CS antibodies and risk of clinical malaria has been described for the first time." (PMID 21079803, 2010). "The best evidence in favour of clonal imprinting in malaria parasites stems from studies on cellular responses to peptide variants of the CS protein." (PMID 19832989, 2009). "Interestingly, the antibodies against synthetic peptides containing the tandem repeated immunodominant epitope of P. vivax and P. falciparum CS proteins were associated to age even in migrant populations with limited exposure to malaria." (PMID 28270152, 2017). "While several previous trials have shown a relationship between anti-CS antibody responses and risk of malaria infection, this study provides the first evidence of a similar relationship between anti-CS antibodies and protection against clinical malaria." (PMID 21079803, 2010). "For malaria, a portion of the Plasmodium yoelii (closely related to Plasmodium falciparum) CS protein was inserted into the fg loop in EDII." (PMID 34577591, 2021). "Rodent malaria Plasmodium berghei parasites, in which the endogenous CS gene has been replaced with the avian Plasmodium gallinaceum CS (PgCS) sequence, develop normally in the A. stephensi mosquito midgut but the sporozoites are not infectious." (PMID 22393411, 2012). "Several species were found positive for CS protein; of these An. sinensis was the main malaria vector in Khe Ngang, where it was most common, while An. harrisoni, An. maculatus and An. sawadwongporni were the main vectors in Hang Chuon." (PMID 20846447, 2010). "Both malaria vaccines were immunogenic for anti-CS antibodies, with RTS,S/AS01B producing a significantly more robust response than RTS,S/AS02A." (PMID 19649245, 2009). "In their study, the prime and boost consisted of a replication-defective recombinant adenovirus expressing the circumsporozoite (CS) protein of Plasmodium yoelii and an attenuated recombinant vaccinia virus expressing the same malaria antigen, VacPyCS, respectively." (PMID 40284919, 2025). "In this regard, avidity that is determined as the antigen-binding ability would be a good indicator, as previous works reported that the anti-CS antibody avidity with the appropriate isotype had a crucial role in mediating protection against malaria in animal model." (PMID 31014347, 2019). "The RTS,S/AS01 malaria vaccine candidate, which has shown significant efficacy against clinical malaria in a large Phase 3 trial, targets the Plasmodium falciparum CS protein, but the ability of serum from vaccinated individuals to inhibit sporogony in mosquitoes has not been evaluated." (PMID 25007730, 2014). "For instance, reciprocal molecular polymorphisms between the human Major Histocompatibility Complex (MHC) and malaria CS genes in West African populations have been identified and the co-distributions of pathogen and host genotypes are consistent with selection pressures exerted on each other." (PMID 17567519, 2007). "Furthermore, an overall decline in the seroprevalence of anti-CS antibodies in 1990 compared to 1987 was reported and may reflect a significant decrease in the number of malaria cases reported by the Brazilian Ministry of Health at that time as a consequence of DDT spraying." (PMID 28270152, 2017). "In this study, the RTS,S/AS01B vaccine demonstrated significantly higher anti-CS antibody responses compared to RTS,S/AS02A confirming observations from a previous study conducted in malaria-naïve adults at the WRAIR." (PMID 19649245, 2009).
malaria (continued). "Subjects who were not infected with malaria during the course of the study exhibited significantly higher anti-CS antibody responses than subjects who became infected." (PMID 19649245, 2009). "The level of anti-CS response to the RTS,S/AS02A vaccine was consistent with previous studies conducted in African adults, and is generally lower than the anti-CS responses to RTS,S/AS02A in malaria-naïve adults and in children." (PMID 19649245, 2009). "This systematic review reveals that IgG antibodies against two parasite proteins, the CS and the MSP119 proteins, of both P falciparum and P. vivax, may be considered as putative biomarkers of malaria exposure in areas with variable and unstable malaria transmission in the Brazilian Amazon." (PMID 28270152, 2017). "Considering that studies enrolling the CS proteins have not been carried out since the early 1990s in endemic Brazilian populations, an interpretation of the potential use of specific antibodies as a biomarker of malaria exposure should be cautiously analysed." (PMID 28270152, 2017). "This study does not support the concept that anti-CS antibodies induced by the RTS,S/AS01 vaccines in humans noticeably reduce malaria transmission by blocking P. falciparum sporozoite development or salivary gland invasion in mosquitoes when taken up during feeding." (PMID 25007730, 2014).